IL4I1 (interleukin 4 induced 1)
Diseases named in the same sentence as IL4I1 in open-access papers (continued):
Sharing a sentence is not in itself a finding about the gene and the disease.
thyroid cancer (1 paper, 2023). "The results revealed that IL4I1 was one of the risk factors in thyroid cancer based on the TCGA database (HR 1.894; 95% CI 1.083–3.310; p = 0.025)." (PMID 37434155, 2023). "Thus, IL4I1 could explain partially the mechanisms underlying tumor metastasis and be a potential diagnostic and prognostic biomarker of thyroid cancer." (PMID 37434155, 2023). "Data from Cancer Genome Atlas (TCGA) and Gene Expression Omnibus (GEO) were analyzed to find out the different mRNA expressions of IL4I1 between thyroid cancer and normal tissues." (PMID 37434155, 2023). "To explore the effects of IL4I1 on the prognosis of thyroid cancer, we first performed the univariate Cox analysis." (PMID 37434155, 2023). "The present study was intended to investigate the effects of IL4I1 on thyroid cancer metastasis and its relationship with the prognosis." (PMID 37434155, 2023). "In conclusion, IL4I1 contributed to tumor metastasis and poor prognosis of thyroid cancer integrating the analysis of TCGA and GSE datasets." (PMID 37434155, 2023). "The expression of IL4I1 mRNA and IL4I1 protein was significantly upregulated in thyroid cancer tissues." (PMID 37434155, 2023). "In this study, we found that IL4I1 was positively related to infiltrating MDSC, Treg, macrophage, and CD8+ T cells, which implied that IL4I1 promoted the metastasis of thyroid cancer by inhibiting the anti-tumor immune response." (PMID 37434155, 2023). "The importance of IL4I1 expression in thyroid cancer metastasis and prognosis promoted us to explore the possible potential mechanism." (PMID 37434155, 2023). "It is interesting that IL4I1 was upregulated in thyroid cancer tissues (p < 0.05), and even higher after (RAI) in GSE151181 database (p < 0.01)." (PMID 37434155, 2023). "Collectively, these data suggest that IL4I1 sustains the proliferation and metastasis potential of thyroid cancers cells in vitro." (PMID 37434155, 2023). "We found and verified the high expression of IL4I1 in thyroid cancer and explored the immune mechanism of its promotion in metastasis." (PMID 37434155, 2023). "KM curves showed that thyroid cancer patients with high-level IL4I1 had a significantly poor prognosis (HR 2.01; 95% CI 1.16, 3.47; p = 0.013)." (PMID 37434155, 2023). "All these data indicated that cancer tissues had abnormally higher expression of IL4I1 in both mRNA and protein levels in thyroid cancer." (PMID 37434155, 2023). "In this study, we found that IL4I1 was highly expressed in thyroid cancer, and IL4I1 was related to malignant tumor types, such as ATC in thyroid cancer and poor prognosis." (PMID 37434155, 2023). "The IHC also showed that IL4I1 protein expression was higher in cancer tissues in thyroid cancer." (PMID 37434155, 2023). "All these data illustrated that IL4I1 could play a particular part in immunocytes infiltration into the tumor microenvironment (TME) in thyroid cancer, which could provide a new perspective on immune escape in thyroid cancer." (PMID 37434155, 2023). "Here, this study reveals that the high level of IL4I1 promoted immune escape and predicted poor prognosis in thyroid cancer, which provides direction for future research into the novel target for immunotherapy, and diagnostic and unfavorable prognostic biomarker." (PMID 37434155, 2023). "What’s more, IL4I1 also predicted the specific immune infiltration in thyroid cancer." (PMID 37434155, 2023). "Finally, we examined the IL4I1 expression in four thyroid cancer cell lines (K1, KTC-1, TPC-1 and 8505C)." (PMID 37434155, 2023). "And high IL4I1 mRNA expression is associated with shorter PFS, which indicated that IL4I1 could be a potential biomarker for poor prognosis in thyroid cancer." (PMID 37434155, 2023). "Here, we intended to explore the correlation between IL4I1 and immune escape in thyroid cancer." (PMID 37434155, 2023). "Hence, we conducted this study and found that IL4I1 expression is upregulated in thyroid cancer both in mRNA and in protein level." (PMID 37434155, 2023).
thyroid cancer (continued). "Moreover, given the overexpression of IL4I1 in thyroid cancer, especially in ATC, we hypothesized that IL4I1 predicted poor survival in thyroid cancer." (PMID 37434155, 2023). "The increased IL4I1 expression is markedly correlated with the immune imbalance in the tumor microenvironment (TME) and predicts poor survival in thyroid cancer." (PMID 37434155, 2023). "Besides, there has been no research on the biological effects of IL4I1 on thyroid cancer." (PMID 37434155, 2023).
tumor (105 papers, 2012 to 2026). "IL4I1, an immunoregulatory enzyme implicated in various cancers, has emerged as a potential biomarker for tumor progression." (PMID 41008831, 2025). "For example, gene ontology (GO) annotations indicated that IL4I1 is associated with leukocyte migration and cell adhesion, both critical processes in tumor inflammation and immune responses." (PMID 41008831, 2025). "For example, tryptophan metabolites have been shown to exert dual roles, namely that they enhance ICB efficacy through modulating tumor-associated macrophages but also promote tumor progression via IL4I1-mediated AhR activation." (PMID 41169397, 2025). "IL4I1 is upregulated in multiple tumor types, associated with poor prognosis, and is more closely associated with AhR activation than IDO expression." (PMID 38339226, 2024). "Using the correlation between IL4I1 and 28 tumor-associated immune cells calculated by a single-sample GSEA algorithm, it was found that IL4I1 was positively correlated with most immune cells, particularly TAM." (PMID 38691253, 2024). "Initially, identified as an early IL-4-inducible gene in B cells, IL4i1 is expressed in primary macrophages, and dendritic cells, and tumor-associated macrophages." (PMID 38605962, 2024). "Our results provide new insights into the functional role of IL4I1 in the pan-cancer setting and highlight the potential mechanism underlying the effects of IL4I1 on the tumor microenvironment and cancer immunotherapy." (PMID 38691253, 2024). "Pyridines: IL4I1, interleukin-4 induced gene 1, encodes ʟ-phenylalanine oxidase IL4I1 present in the tumor bed of a vast diversity of human tumor types." (PMID 39109294, 2024). "IL4i1 is expressed in monocyte-derived DCs, macrophages residing in granulomas, tumor-associated macrophages (TAMs), microglia, and B cells, where the enzyme was initially discovered." (PMID 37196768, 2023). "It was reported that the immunometabolism associated enzyme interleukin-4-induced-1 (IL4I1) was related to tumor metastasis." (PMID 37434155, 2023). "L-amino acid oxidase IL-4-induced-1 (IL4I1) is an enzyme found to be associated with AhR induced gene expression more than other tryptophan catabolic enzymes in human tumours." (PMID 34944851, 2021). "IL-4 induced gene 1 (IL4I1) is an L-amino acid oxidase with immunomodulatory properties originally described in B cells and then in dendritic cells (DCs) and tumor-associated macrophages (TAMs)." (PMID 34068423, 2021). "We propose that components of the pro-tumor effects of IL4i1 are linked to local anti-ferroptotic effects on transformed cells." (PMID 33646117, 2021). "Overall, IL4I1 is implicated in diminishing anti-tumour CD8+ T-cell responses, thereby promoting resistance to ICB." (PMID 34944851, 2021). "In accordance with this function, the IL4I1 gene was shown to be associated with a poor prognosis in a transcriptomic study of the micro-dissected tumor stroma of human breast cancers." (PMID 29206151, 2017). "IL4I1 is expressed in tumor-associated macrophages of most human cancers and in some tumor cell types." (PMID 29206151, 2017). "Moreover, elevated IL4I1 expression has been reported as a hallmark of an inflamed tumor microenvironment (TME) and has been correlated with improved responses to immunotherapy." (PMID 41280919, 2025). "Similarly, IL4I1-deficient mice challenged with chronic lymphocytic leukemia present with reduced tumor burden, which is accompanied by enhanced CD8+ T-cell functionality and reduced frequency of total and activated regulatory T cells." (PMID 39211039, 2024). "High expression of IL4I1 is associated with the state of tumor immunosuppression and may contribute to tumor-associated macrophage invasion." (PMID 38691253, 2024). "In addition, the level of tumor-associated macrophage infiltration was positively correlated with the expression of IL4I1 in pan-cancerous tissues." (PMID 38691253, 2024). "IL4I1 is an immune-associated enzyme secreted by tumor cells." (PMID 37434155, 2023).
tumor (continued). "For example, IL4I1 (interleukin 4 induced 1) protein may play a role in immune system escape as it is expressed in tumour-associated macrophages and it was described as a metabolic immune checkpoint which promotes tumour progression." (PMID 37875584, 2023). "Immune checkpoint blockade (ICB) could induce IL4I1 and IDO1, whereas IL4I1-deficient mice model showed a reduced Treg frequency and tumor burden, indicating the role of IL4I1 in immune escape." (PMID 35962343, 2022). "In our study, we linked IL4I1 to tumor intrinsic malignant properties." (PMID 34717685, 2021). "Furthermore, leukaemic cell lines overexpressing IL4I1 promote the M2 polarisation of tumour-associated macrophages in vitro." (PMID 34944851, 2021). "Furthermore, IL4I1 expressed in tumor-associated myeloid cells was involved in immune evasion of cancer cells." (PMID 30419821, 2018). "Furthermore IL4I1 is strongly expressed by tumor-associated macrophages of most types of cancer and has been proposed to play a role in the escape of tumors from specific immune responses." (PMID 29206151, 2017). "IL4I1 activity has been implicated in shaping immunosuppressive tumor microenvironments, suggesting that integrating IL41 expression and kynurenic acid measurements into future analyses may provide additional insights into the broader landscape of tryptophan metabolism and immune remodeling in LUAD." (PMID 40427178, 2025). "Lao1 (L-amino acid oxidase, interleukin 4-induced 1, IL4I1) was the only common DEG according to the comparisons of tumor expression profiles between mice that were given UBCS039 or DMSO and between mice that were given UBCS039 or PBS." (PMID 41530841, 2026). "The elevated expression of IL4I1 enhances the degradation of branched-chain amino acids, promoting tumor growth and metastasis." (PMID 41822356, 2026). "In future treatment regimens, it will be necessary to screen patients in whom the tryptophan metabolism pathway or IL4I1 contributes to tumor progression to better devise blocking strategies." (PMID 40103267, 2025). "Overexpression of IL4I1 can promote tryptophan catabolism, which suppresses the activity of T cells and NK cells, thereby helping tumor cells evade immune surveillance." (PMID 41008831, 2025). "Western blot analysis revealed that the wild‐type (WT) and K351A mutant forms of IL4I1 were expressed at similar levels in IL4I1‐WT and K351A‐expressing tumor cells." (PMID 40583248, 2025). "Cell death remarkably increased in the Nrf2 knock‐down group, IL4I1‐overexpression was still able to prevent ferroptosis in tumour cells, however, this ability was obviously weakened when compared with that of the Nrf2 expressing group." (PMID 40071723, 2025). "IL4I1 is a tryptophan-metabolizing enzyme that depletes tryptophan and generates immunomodulatory metabolites in tumor microenvironment." (PMID 40083932, 2025). "Functional assays confirmed that IL4I1 promotes tumor cell proliferation, migration, and invasion, and is correlated with an immunosuppressive tumor microenvironment." (PMID 41008831, 2025). "Beyond activation by endogenous or exogenous factors, mechanical stress enhances hepatocyte IL4I1, activating AhR signaling to drive tumor progression and recurrence." (PMID 40559961, 2025). "HE staining also revealed that larger and more blood vessels infiltrated the tumour in the IL4I1‐overexpression group, suggesting more malignant biological processes in the IL4I1‐overexpression group." (PMID 40071723, 2025). "Overexpression of the Trp metabolic enzyme interleukin‐4‐induced gene‐1 (IL4I1) in tumor cells increases intracellular levels of I3A and enhances tumor immunogenicity." (PMID 40583248, 2025).
tumor (continued). "Bioluminescence imaging at days 7 and 21, respectively, showed that the tumour grew significantly faster in the IL4I1‐overexpression group compared with the control group." (PMID 40071723, 2025). "Collectively, these results suggest that tumor‐intrinsic I3A would enhance tumor immunogenicity, meanwhile IL4I1 overexpression increased tumor immunogenicity by increasing intracellular I3A production." (PMID 40583248, 2025). "The expression of IL4I1 across various tumor types reveals a complex relationship with disease prognosis." (PMID 41008831, 2025). "Regulatory B cells (Bregs), regulated by c-Maf and IL4I1, contribute to immunosuppression and tumor progression, whereas overall B cell activity remains context-dependent." (PMID 41465101, 2025). "Knockout of IL4I1 inhibited proliferation, migration, and invasion in vitro and tumor growth in vivo." (PMID 41008831, 2025). "For the analysis, the TMA cores were evaluated by an experienced head and neck pathologist and the mean expression of IDO1 and IL4I1 in the tumor was calculated and used for the subsequent analysis." (PMID 40332319, 2025). "We conducted a correlation analysis to examine the relationship between human tumor‐intrinsic expression of IL4I1 and tumor immunogenicity factors such as MHC‐I expression and Cytotoxic T lymphocyte (CTL) activation." (PMID 40583248, 2025). "IL4I1 is known to promote tumor cell proliferation and suppress immune responses, and it was observed to enhance immune suppression via the IDO1-AHR-Kyn metabolic pathway." (PMID 41219641, 2025). "In cancer development, IL4I1 regulates the tumor microenvironment, promotes immune evasion, and enhances tumor cell proliferation and metastasis, showing great potential as a therapeutic target." (PMID 41008831, 2025). "Meanwhile, tumor‐intrinsic expression of IL4I1 metabolic enzyme also catalyzed Trp metabolism to I3A and increased tumor immunogenicity." (PMID 40583248, 2025). "A study by Christiane A. Opitz and colleagues identified, through screening and analyzing a broad range of tumor cases, the highest correlation between IL4I1 and AHR activity." (PMID 38755125, 2024). "scRNA-seq analysis suggested that IL4I1 differ significantly among different cells in the tumor microenvironment and was most enriched in macrophages." (PMID 38691253, 2024). "Interleukin 4 induced protein 1 (IL4I1) is an amino acid oxidase that plays a significant role in facilitating immune evasion of tumor cells through the enhancement of tryptophan metabolism." (PMID 38853203, 2024). "Next, we investigated differences in the methylation of IL4I1 and binding proteins between tumor and normal tissues in 14 cancer types." (PMID 38691253, 2024). "We further examined the TCGA-BLCA cohort for correlations between IL4I1 and various immunological characteristics of tumor microenvironment (TME), such as cancer immune cycle, immune cell infiltration, immune checkpoint expression and T cell inflamed score." (PMID 38873416, 2024). "The expression of IL4i1 seems to be involved in phagocytic processes, as IL4i1+ macrophage population coexists with the genes involved in phagosome maturation in the tumor microenvironment (TME)." (PMID 38605962, 2024). "Tumor tissue data from TCGA and normal tissue data from TCGA and GTEx databases were initially used to evaluate IL4I1 expression." (PMID 38691253, 2024). "IL4I1 is an enzyme that oxidizes phenylalanine and has been described as a metabolic immune checkpoint that promotes tumor progression." (PMID 38790160, 2024). "Our results demonstrate a major cell autonomous component in limiting tumor growth by Trp starvation and in the pro-tumoral role of IL4I1 in HCC." (PMID 38769298, 2024).